AHR (aryl hydrocarbon receptor)
Diseases named in the same sentence as AHR in open-access papers (continued):
Sharing a sentence is not in itself a finding about the gene and the disease.
wasting syndrome (12 papers, 2011 to 2025). "In contrast, the P. aeruginosa pigment molecule, pyocyanin, also an AHR activator, caused inhibition of adipogenesis resulting in wasting syndrome." (PMID 32730300, 2020). "Surprisingly perhaps, modern research still continues to uncover additional ways by which TCDD induces wasting syndrome via the AHR, one example being through the regulation of TCDD-inducible poly(adenosine diphosphate-ribose) polymerase gene expression." (PMID 33374508, 2020). "By the turn of the century, a mechanism had emerged for how TCDD exposure led to the wasting syndrome, presumably through the actions of the AHR." (PMID 33374508, 2020). "Toxic effects of dioxins mediated by the aryl hydrocarbon receptor (AhR) include the wasting syndrome, the induction of oxidative damage, hepatic injury and carcinogenesis." (PMID 21599895, 2011). "Chronic activation of KP in cachexia leads to muscle wasting through multiple pathways, including activation of the aryl hydrocarbon receptor (AhR) pathways that induce muscle-specific E3 ubiquitin ligases (e.g., MAFbx/atrogin-1) that cause proteasomal degradation." (PMID 40869331, 2025). "However, an intact AHR signaling pathway is absolutely required for TCDD-induced wasting syndrome." (PMID 34129049, 2021). "Neither wasting syndrome nor CYP1A1 induction in the fetal brain caused through the activation of aryl hydrocarbon receptor (AhR) could be attenuated by LA." (PMID 22911699, 2012). "Tiparp−/− and TiparpHep−/− mice exhibit increased AHR activity and increased sensitivity to TCDD-induced toxicities and wasting syndrome." (PMID 34129049, 2021). "As the initial characterization of the AH locus and the AHR protein developed throughout the 1970s and 1980s, the mechanism via which TCDD induces wasting syndrome in animals was also under close investigation." (PMID 33374508, 2020). "The chronic activation of KP in cachexia leads to muscle wasting through multiple pathways, including activation of KYN-aryl hydrocarbon receptor (AhR) pathways that induce muscle-specific E3 ubiquitin ligases (e.g., MAFbx/atrogin-1), which cause proteasomal degradation." (PMID 40869331, 2025). "Taken in conjunction with levels of Me1 and Pdk1, it appears that AHR-less-active animals may preferentially utilize nitrogenous molecules as sources of energy and that this preference may somehow confer a protective effect against TCDD-induced wasting syndrome." (PMID 25467400, 2014). "This may be a pathway not directly influenced by the AHR, which could explain the increased resistance of these animals to TCDD-induced wasting syndrome." (PMID 25467400, 2014).
coronary artery disease (11 papers, 2017 to 2025). "There are some data indicating that exposure to exogenous ligands of AhR (either dioxins or polycyclic aromatic hydrocarbons) raises the risk of coronary heart disease." (PMID 39000041, 2024). "Along the same lines, AhR expression has been linked to the incidence of coronary arterial disease in an epidemiological study on a Chinese population." (PMID 32009975, 2019). "AhR expression and polymorphisms were also associated with risk of coronary arterial disease in a Chinese population." (PMID 31439044, 2019). "They found increased AhR mRNA expression in coronary arterial disease patients compared to controls and suggested AhR as a diagnostic biomarker for coronary arterial disease." (PMID 32009975, 2019). "A study at Stanford University reported that the transcription factor TCF21 promoted the expression of inflammation-related genes in human coronary artery smooth muscle cells via interaction with AhR, leading to an increased risk for coronary artery disease." (PMID 29984241, 2018). "Disruption of AHR signaling is associated with several diseases, including prostate and coronary artery disease." (PMID 29494622, 2018). "Further analysis of AhR polymorphisms found that AhR rs2066853 showed a significant correlation with the risk for coronary artery disease." (PMID 29984241, 2018). "Circulating AhR is upregulated in patients with coronary heart disease, and polymorphisms of the AhR gene may mediate the risk of this disease." (PMID 39000041, 2024). "Exposure to exogenous ligands of AhR, such as dioxin (2,3,7,8-tetrachlorodibenzop-dioxin, TCDD), increases the risk of ischemic heart disease and cardiovascular mortality." (PMID 40508196, 2025). "In a study of coronary heart disease, mimic transfection of miR-31 increased the levels of AhR and IL-22 and promoted Th22 cell differentiation." (PMID 36809070, 2023). "Previous studies have demonstrated that AhR pathway is a potential therapeutic target for ischemic heart disease." (PMID 37749614, 2023). "AhR expression, presented as mRNA extracted from peripheral blood mononuclear cells, was higher in patients with coronary artery disease than in controls." (PMID 37749614, 2023). "Compared with controls, blood levels of AhR were found to be significantly increased in patients with coronary arterial disease." (PMID 31439044, 2019). "There is evidence to indicate that exposure to exogenous ligands of AhR, such as dioxin, TCDD, and coplanar polychlorinated biphenyls, increase the risk for ischemic heart disease." (PMID 29984241, 2018). "A study examined the role of AhR in coronary artery disease susceptibility in a Chinese population, and the results suggested that expression of circulating AhR was elevated in patients with coronary artery disease." (PMID 29984241, 2018). "For instance, allele rs55730499-T associated with increased level of LDL-C and the risk of coronary artery disease was predicted to create binding sites for transcription factors acting as activators (NR1H, AHR::ARNT, IRF) or repressors (HAND1) of gene expression." (PMID 35203469, 2022). "Taken together, the findings suggest that AhR may be an important gene or drug target for the prevention and treatment of ischemic heart disease." (PMID 29984241, 2018). "After intersection of AHR with ARNT and TCF21 the only remaining categories were coronary artery disease and coronary artery calcification, narrowing the importance of the interaction of AHR/ARNT and TCF21 factors to pathophysiological processes in cardiovascular disease." (PMID 28481916, 2017).
infertile (11 papers, 2013 to 2023). "Relevant to the current study, increased spermatocyte AhR expression has been linked to infertility in humans and toxicant exposure in adult rats." (PMID 25127480, 2014). "Our data is consistent with studies from others indicating heightened expression of spermatocyte AhR in association with infertility in men and enhanced AhR expression in the spermatocytes of rats exposed in vivo to another environmental endocrine disruptor, BaP." (PMID 25127480, 2014). "The overexpression of AhR we observed in infertile subjects has been previously reported in Sertoli, Leydig and spermatid cells of infertile men." (PMID 26445054, 2015). "A difference between infertile and fertile subjects was observed only for AhR, its expression being significantly higher in infertile men from the metropolitan area compared to fertile subjects of the same area." (PMID 26445054, 2015). "In fact, infertile women had higher levels of all the NRs compared to fertile women, whereas infertile men had only higher AhR levels than fertile subjects." (PMID 26445054, 2015). "In infertile women, a positive association was found between BPA and MEHP levels and ERα, ERβ, AR, AhR, and PXR expression." (PMID 23710174, 2013). "AhR-null mice exhibit infertility, abnormalities in liver and cardiovascular problems such as a defective closure of the ductus venosus, indicative of the implication of the AhR in various developmental processes." (PMID 23301081, 2013). "The high level of benzo(a)pyrene in the infertile group could serve as a predictive marker for idiopathic infertility along with the signature proteins AhR and the HSPs, particularly the HSP90." (PMID 37261076, 2023). "Therefore, our results may lend further support to AhR overexpression as a characteristic of infertility in males." (PMID 26445054, 2015). "Indeed, infertile women from metropolitan area presented a significant 10-fold increase, with respect to fertile women, in the gene expression levels of five out of six analyzed NRs, namely ERα, ERβ, AR, AhR and PXR." (PMID 25268510, 2014). "The analysis of the correlation between EDs concentration and the NRs expression in blood evidenced that, in both infertile and fertile men, PFOA levels were negatively correlated to the expression of ERα, ERβ, AR, AhR and PXR." (PMID 26445054, 2015). "Expression levels of ERα, ERβ, AR, AhR and PXR were significantly higher in infertile subjects from the metropolitan area compared to the other two areas, showing the pattern metropolitan > urban > rural areas." (PMID 26445054, 2015). "In particular, BPA and MEHP levels, as well as expression of ERα, ERβ, AR, AhR and PXR were more prevalent in infertile women from the metropolitan area." (PMID 25268510, 2014). "The subjects from the metropolitan area are characterized by higher internal levels of BPA as well as gene expression of ERα, ERβ, AR AhR and PXR; moreover, only in this area infertile men had higher BPA and PFOS levels, as well as AhR expression, compared to fertile subjects." (PMID 26445054, 2015). "On the other hand, while a significant negative correlation between PFOA and all NRs included in the panel, with the exception of PPARγ, was found in infertile men, in infertile women such negative correlation was observed only with AhR." (PMID 26445054, 2015). "Indeed, we observed that ERα, ERβ, AR, AhR and PXR expression is correlated positively with BPA levels and negatively with PFOA levels, in both infertile and fertile subjects." (PMID 26445054, 2015). "Moreover, our results point out a panel of NRs (ERα, ERβ, AR, AhR and PXR) induced at the same time in PBMCs of infertile subjects." (PMID 25268510, 2014). "BPA serum concentration showed a positive correlation with ERα, ERβ, and AR in both fertile and infertile women, although the strength of this association appeared higher in the infertile group; moreover, in infertile women, BPA showed a specific, positive correlation with AhR and PXR expression." (PMID 23710174, 2013).
infertile (continued). "A positive association between BPA levels and AhR (r = 0.335; P < 0.005) and PXR expression (r = 0.429; P < 0.0005) was also demonstrated among infertile women, but not in controls." (PMID 23710174, 2013). "Only PFOA levels showed negative correlations with AhR (r = −2.242; P < 0.05) in infertile women." (PMID 23710174, 2013). "A positive correlation was found also between MEHP and ERα (r = 0.388; P < 0.005), ERβ (r = 0.398, P < 0.005), AR (r = 0.366; P < 0.005), AhR (r = 0.291; P < 0.05), and PXR expression (r = 0.364; P < 0.005) in the infertile group, but not in the control group." (PMID 23710174, 2013).
ischemic stroke (11 papers, 2017 to 2025). A stroke disorder caused by obstruction of blood flow to the brain, due to thrombotic (local blood clot formation) or embolic (due to a blood clot or other material traveling from another site) event. "Additionally, recent results indicate that pharmacological or genetic loss of the aryl hydrocarbon receptor (AhR) is neuroprotective in ischemic stroke." (PMID 28523230, 2017). "In murine models of various diseases, including experimental autoimmune encephalomyelitis, ischemic stroke, intracerebral hemorrhage, and LPS-induced neuroinflammation, AHR expression is increased in various brain-resident cells, including microglia." (PMID 40821767, 2025). "Conditional AHR knockout in neural stem/progenitor cells attenuates astrogliosis and microgliosis in ischemic stroke models, whereas microglia- or astrocyte-specific AHR deletion worsens EAE." (PMID 40821767, 2025). "Following ischemic stroke, the intestinal flora activates microglia by producing endogenous AHR (aryl hydrocarbon receptor) ligands and SCFAs, which exert neuroprotective effects." (PMID 40723792, 2025). "This aligns with reports that AHR antagonists (6,2,4′-trimethoxyflavone) protect against ischemic stroke by blocking microglial activation and preserving neurogenesis, while indoxyl sulfate promotes neurotoxic environments in glial co-cultures." (PMID 40821767, 2025). "Microbiota-derived ligands of AHR are decreased in the human plasma at 24 hours after ischemic stroke." (PMID 37790313, 2023). "Our study builds on the concept that differential activation of MG AHR by host-derived versus microbiome-derived metabolites affects outcomes after ischemic stroke." (PMID 37790313, 2023). "Our novel findings provide compelling evidence that the restoration of a well-balanced pool of host-derived kynurenine-based and microbiota-derived indole-based ligands of AHR holds considerable therapeutic potential for the treatment of ischemic stroke." (PMID 37790313, 2023). "On the other hand, in ischemic stroke models, AhR exacerbates infarct formation, and downregulated IL-1β and IL-6 expression was detected in AhR KO mice." (PMID 36797786, 2023). "As an important regulator in the “microbiota-gut-brain” axis, AHR has the potential to be used as a new therapeutic target for ischemic stroke treatment." (PMID 36032153, 2022). "Movement disorder after ischemic stroke induction was also alleviated in AhR KO mice." (PMID 36797786, 2023). "Recently, AhR was reported to exacerbate infarct formation induced by ischemic stroke." (PMID 33804845, 2021). "Here, we investigate the AHR-mediated neuroglial activities in the model of acute ischemic stroke using the nestin+ cell-specific knockout of AHR (with spared microglia) and pharmacological inhibition of AHR to assess how astrogliosis and neurogenesis are modulated in acute ischemic injury." (PMID 31606043, 2019). "In this review, we discuss the research progress on AHR regarding its role in ischemic stroke and prospects to be used as a therapeutic target for ischemic stroke treatment, aiming to provide a potential direction for the development of new treatments for ischemic stroke." (PMID 36032153, 2022). "AhR might be a pharmacological target for improving prognosis after ischemic stroke." (PMID 33804845, 2021). "CRM28 exposure did not affect the prognosis of ischemic stroke in null mice for aryl hydrocarbon receptor, a polycyclic aromatic hydrocarbon (PAH) receptor." (PMID 36797786, 2023). "LXA4 is a ligand for AhR and it is possible that a high dose of BML‐111 activates pathways downstream of AhR that contribute to negative outcomes in ischemic stroke." (PMID 28523230, 2017). "Furthermore, there have been no reports regarding the optimal timing of inhibition of AhR, which is an important consideration in the context of ischaemic stroke." (PMID 32913241, 2020).
pituitary adenomas (11 papers, 2007 to 2022). "A modifying effect of AhR or AIP polymorphisms in addition to contaminant exposure was associated in acromegaly patients with pituitary adenoma size, biological aggressiveness and resistance to somatostatin analogs." (PMID 37435457, 2022). "This is the first report of an AHR variant with predicted pathogenicity in the pituitary adenoma setting." (PMID 31996203, 2020). "Our group showed that the germline single nucleotide polymorphism (SNP) rs2066853 of the AHR encoding gene is more frequent in acromegaly patients as compared to sex- and age-matched healthy subjects and is associated with increased pituitary adenoma invasiveness and secondary neoplasm’s risk." (PMID 33281746, 2020). "Over-expression of AhR in pituitary adenoma (PA) cells revealed potential tumor suppressor activity independent of exogenous ligand activation by BaP." (PMID 33451095, 2021). "Subsequently, several groups focused their attention on the uncovered link between AHR and/or AIP expression and the molecular mechanisms underlying pituitary adenoma pathogenesis." (PMID 33281746, 2020). "By immunohistochemical methods, it was shown that the AhR protein is less abundant in samples of pituitary adenomas compared to samples of a normal pituitary gland, and its amount correlates with AIP expression." (PMID 32325928, 2020). "Most studies on the genetic predisposition to pituitary adenoma have dealt with the partner protein of AhR (AIP), which, like AhR, is expressed in the normal human pituitary gland." (PMID 32325928, 2020). "Evidence is now reported of the equally important function of AhR in the regulation of the growth, proliferation, and apoptosis of pituitary cells and in the formation or progression of human pituitary adenomas." (PMID 32325928, 2020). "Thus, the participation of AIP in the cytoplasmic stabilization of AhR in the human pituitary gland is confirmed, and accordingly, so is the destabilization of AhR during AIP deficiency, which can occur in pituitary adenomas carrying mutant inactive AIP." (PMID 32325928, 2020). "AHR appears to act as tumor suppressor in GH-secreting pituitary adenomas (PA)." (PMID 33281746, 2020). "Germline mutations of aryl hydrocarbon receptor interacting protein (AIP), a gene coding for a cytoplasmic interaction partner of aryl hydrocarbon receptor (AHR) (also known as dioxin receptor), were recently described to cause low-penetrance pituitary adenoma predisposition (PAP)." (PMID 17242703, 2007).
acne (10 papers, 2020 to 2025). An inflammatory process of the sebaceous glands which is characterized by comedones, nodules, papules and/or pustules on the skin. "Third, an increasing body of evidence underscores the significance of C. acnes-mediated activation of the aryl hydrocarbon receptor (AhR) pathway in acne pathogenesis." (PMID 37344849, 2023). "Deficiency of intestinal probiotics in acne vulgaris patients would lead to decreased Trp metabolites, such as IAId, IAA, and ILA, and weakened activation of AhR and GPCR on the Mφ surface." (PMID 35966699, 2022). "In recent years, several studies have been performed linking the expression of AhR and the appearance of acne." (PMID 34944067, 2021). "In our experiment, we first demonstrated that treatment with IAA and indole may suppress the expression of inflammatory factors in acne vulgaris by the AhR pathway in both in vivo and in vitro." (PMID 38250060, 2023). "Finally, the roles of IAA and indole in alleviating acne vulgaris were confirmed both in vitro and in vivo, which could be reversed by AhR inhibitors." (PMID 38250060, 2023). "Microbial Trp metabolites may enter the peripheral circulation through the intestinal mucosa in the area of acne lesions, activate the AhR and GPCR-induced signaling, attenuating Mφ polarization, activation of ILCs and secretion of inflammatory factors by Treg cells." (PMID 35966699, 2022). "A previous study showed that the aryl hydrocarbon receptor promotes secretion of inflammatory factors TNF-α and IL-8 in human SZ95 sebocytes, which indicates a possible mechanism in TLR2-mediated acne." (PMID 32685503, 2020). "Additionally, the AhR is able to modulate TLR2-mediated expression of TNF-α and IL-8 in human sebocytes, thereby highlighting its role in acne inflammation." (PMID 37344849, 2023). "Moreover, C. acnes inhibits lipogenesis and promotes the differentiation of sebocytes, effects that are negated by AhR gene silencing, suggesting a non-acnegenic role of C. acnes in promoting acne remission via the AhR pathway." (PMID 37344849, 2023).